RNU6-20P (RNA, U6 small nuclear 20, pseudogene)
Synonyms: RNU6-20
Gene: Small nuclear RNA gene on chromosome 16 (57,830,536 to 57,830,642, reverse strand). Ensembl gene ENSG00000206833.
Homologues: Orthologues: chimpanzee U6 (99% identical), rabbit U6 (97% identical), rat U6 (97% identical), macaque U6 (96% identical), mouse Gm24701 (89% identical), guinea pig U6 (88% identical), mouse Gm25354 (88% identical), dog U6 (81% identical), guinea pig U6 (73% identical). Paralogues in human: RNU6-25P (97% identical), RNU6-1 (96% identical), RNU6-2 (96% identical), RNU6-35P (96% identical), RNU6-3P (96% identical), RNU6-4P (96% identical), RNU6-5P (96% identical), RNU6-6P (96% identical), RNU6-9 (96% identical), RNU6-1145P (95% identical), RNU6-12P (95% identical), RNU6-1316P (95% identical), and 1286 more.